CCL13 (C-C motif chemokine ligand 13)
Diseases named in the same sentence as CCL13 in open-access papers (continued):
Sharing a sentence is not in itself a finding about the gene and the disease.
Cirrhosis (2 papers, 2022 to 2023). A chronic disorder of the liver in which liver tissue becomes scarred and is partially replaced by regenerative nodules and fibrotic tissue resulting in loss of liver function. "Elevated CCL13 may be a protective factor and needs to be further investigated, given that Gram-negative bacteria are more frequently seen in bacterial infections associated with cirrhosis." (PMID 37153575, 2023). "It should be noted that elevated CCL13 may be linked to antimicrobial resistance, and it ought to take this into account given the potential of CO infections like COPD and cirrhosis." (PMID 37153575, 2023). "Although little is known about CCL13’s role in the development of cirrhosis, recent research suggests that it may slow the advancement of the disease through type 2 immunity." (PMID 37153575, 2023).
colorectal cancer (2 papers, 2022 to 2023). A primary or metastatic malignant neoplasm that affects the colon or rectum. "High blood CCL13 levels were independently a marker for predicting distant metastasis in colorectal cancer, according to logistic regression analysis, and they were substantially linked with advanced age, advanced T-stage, distant metastasis, and UICC stage in colorectal cancer." (PMID 37153575, 2023).
glioma (2 papers, 2016 to 2021). A benign or malignant brain and spinal cord tumor that arises from glial cells (astrocytes, oligodendrocytes, ependymal cells). "CXCL10, CCL13, SAA1, and CCL27 were more highly expressed in elderly, high‐grade, 1p19q non‐codel, IDH‐wildtype glioma patients, while SSTR5, CCL21, and HTR1A expressions were low in these malignant clinicopathological features of gliomas." (PMID 33503296, 2021). "In previous studies, the molecular mechanisms of HTR1A, CCL13, CCL21, and CCL27 in gliomas remained unclear." (PMID 33503296, 2021).
hepatocellular carcinoma (2 papers, 2020 to 2023). A malignant tumor that arises from hepatocytes. "Likewise, hepatocellular carcinoma (HCC) tumor tissues contain considerably more CCL13 mRNA than normal tissue, however this is unrelated to the clinical prognosis." (PMID 37153575, 2023).
leukaemia (2 papers, 2022 to 2024). "Res and ω-3 PUFA reduced IL-1β, IL-6, TNF-α, CXCL10/IP-10, CCL13/MCP-4 and CCL20/MIP-3α in LPS/IFN-γ activated human leukaemia THP-1 cells, which is indicative of a dampening effect on M1 macrophages." (PMID 35884829, 2022).
lymph node metastasis (2 papers, 2022). "Furthermore, the levels of CCL13 in the serum and tumor tissues of OSCC patients with lymph node metastasis were significantly higher than those in OSCC patients without metastasis." (PMID 36291863, 2022).
mild cognitive impairment (2 papers, 2012 to 2025). "Two studies reported significantly different concentrations of markers in individuals with MCI: CXCL11, CCL13, and CCL15 were increased, and CXCL16 and IL-16 were decreased in individuals with mild cognitive impairment compared to controls." (PMID 40711681, 2025). "We therefore measured the levels of CCL2 and three other CCR2 ligands, i.e. CCL11 (eotaxin), CCL13 (MCP-4) and CCL26 (eotaxin-3), in the cerebrospinal fluid (CSF) and plasma of 30 controls and 119 patients with mild cognitive impairment (MCI) at baseline." (PMID 22303443, 2012).
multiple myeloma (2 papers, 2017 to 2025). "Several studies suggest that CCL13 is associated with 2-microglobulin (2-MG) levels in multiple myeloma and cell proliferation in BRCA." (PMID 40692603, 2025).
multiple sclerosis (2 papers, 2005 to 2023). A progressive autoimmune disorder affecting the central nervous system resulting in demyelination. "We also give an overview of research that found very little evidence of CCL13 in HIV, nephritis, and multiple sclerosis." (PMID 37153575, 2023).
onchocerciasis (2 papers, 2013 to 2022). Onchocerciasis is a form of filariasis, caused by the parasitic worm Onchocerca volvulus, transmitted by the black fly. "Following treatment of onchocerciasis patients with ivermectin, Eotaxin-2/CCL24 and MCP-4/CCL13 enhanced suggesting that these chemokines facilitated clearance of O. volvulus microfilariae by monocytes and eosinophil granulocytes." (PMID 23855879, 2013). "As previously observed in onchocerciasis patients, the serum concentrations of MCP-4 (CCL13) increased 3 days post initial ivermectin treatment and this may signify ongoing effector cell activation against microfilariae of O. volvulus." (PMID 35503786, 2022).
osteoarthritis (2 papers, 2021 to 2025). A noninflammatory degenerative joint disease occurring chiefly in older persons, characterized by degeneration of the articular cartilage, hypertrophy of bone at the margins and changes in the synovial membrane. "We performed immunohistochemical staining to explore the expression patterns of chemokines (CCL13, CCL18, and CCL3) in the synovial membrane of RA subgroups, while the osteoarthritis (OA) synovial membrane was used as controls." (PMID 34404786, 2021).
post-traumatic stress disorder (2 papers, 2017 to 2023). An anxiety disorder precipitated by an experience of intense fear or horror while exposed to a traumatic (especially life-threatening) event. "In individuals with post-traumatic stress disorder (PTSD), there is an increase in serum levels of CCL13, CCL20, and CXCL6, which may indicate a higher risk for developing PTSD." (PMID 37153575, 2023).
rheumatic diseases (2 papers, 2023 to 2024). "In conclusion, while CCL13 cannot be used to diagnose rheumatism, it may be coupled with other disease-specific markers to increase the accuracy of the diagnosis." (PMID 37153575, 2023).
abdominal aortic aneurysm (1 paper, 2020). Enlargement and ballooning of the vessel that supplies arterial blood to the abdomen, pelvis and legs. "Moreover, studies of coronary atherosclerosis and abdominal aortic aneurysm showed that miR-103 played a novel role in negatively regulating inflammatory pathways through targeting chemokine (C-C motif) ligand 13 (CCL13) and ADAM metallopeptidase domain 10 (ADAM10) respectively 55,56." (PMID 32549769, 2020).
acute pancreatitis (1 paper, 2024). An acute inflammatory process that leads to necrosis of the pancreatic parenchyma. "Additionally, we have discovered three inflammatory proteins that are also associated with the occurrence of acute pancreatitis, namely interleukin-15 receptor subunit alpha (IL-15RA), monocyte chemoattractant protein-4 (CCL13), and tumor necrosis factor receptor superfamily member 9 (TNFRSF9)." (PMID 38881734, 2024). "Inflammatory proteins CCL13 and TNFRSF9 also play a promoting role in the development of acute pancreatitis." (PMID 38881734, 2024). "Among these, genetically predicted IL-15RA, monocyte chemoattractant protein-4 (CCL13), and tumor necrosis factor receptor superfamily member 9 (TNFRSF9) showed a significant positive correlation with the occurrence of acute pancreatitis." (PMID 38881734, 2024).
AIDS (1 paper, 2023). A syndrome resulting from the acquired deficiency of cellular immunity caused by the human immunodeficiency virus (HIV). "According to a multicenter AIDS cohort study, CCL13 detectability was found to be greater than 80%, and elevated plasma levels of CCL13 may be associated with more rapid disease progression in HIV-infected individuals." (PMID 37153575, 2023).
atrophic gastritis (1 paper, 2020). "In an atrophic gastritis environment, the expression of CXCL14, CCL4, CCL26, CCL21, CCL2, CCL19, and CCL13 was correlated with the infiltration of central memory CD4 T cell." (PMID 33426088, 2020).
bladder cancer (1 paper, 2025). "Conversely, high levels of other chemokines like CCL5, CCL8, CCL13, and CCL18 have been correlated with improved outcomes in bladder cancer patients." (PMID 39964621, 2025).
glioblastoma (1 paper, 2024). The most malignant astrocytic tumor (WHO grade IV). "Furthermore, glioblastoma cells release CCL13 in response to IL1β secretion by tumour-associated macrophages (TAMs), leading to monocyte recruitment and their differentiation into TAMs." (PMID 39315158, 2024).
liver disease (1 paper, 2022). "Since CCL13 can bind to several chemokine receptors (CCR1, CCR2, CCR3, CCR5, or CCR11), it should have similar properties as other ligands of these receptors in the liver disease, but further studies are needed." (PMID 35281057, 2022). "Although a variety of chemokines have been well studied in various diseases, there is no comprehensive review presenting the roles of all known chemokine ligands of CCR2 (CCL2, CCL7, CCL8, CCL12, CCL13, CCL16, and PSMP) in liver disease, and this review aims to fill this gap." (PMID 35281057, 2022). "However, there is no published research showing the importance of CCL13 in liver disease." (PMID 35281057, 2022). "However, other ligands of CCR2 have not been thoroughly studied in liver diseases, especially CCL7, CCL8, CCL12, CCL13, CCL16, and PSMP." (PMID 35281057, 2022).
lymphopenia (1 paper, 2025). Reduction in the number of lymphocytes. "At month three, LC patients had elevated IL10RB and MCP-1, whereas by month six, levels of several proteins (monocyte chemoattractant proteins MCP2/CCL8 and MCP4/CCL13, lymphopenia associated IL2RB, and TGF-signaling LAP/TGFb1) had fallen." (PMID 40572685, 2025).
membranous nephropathy (1 paper, 2025). "Its results showed significantly increased mRNA expression of CCL13 in all the included patients with relapse compared to those in remission, patients with membranous nephropathy, and healthy controls." (PMID 39996798, 2025).
neuromyelitis optica spectrum disorder (1 paper, 2018). "Adjusted regression coefficients (β) of CCL13, CCL11, and CCL26 levels with relapse times, ARR, and EDSS scores as outcomes in neuromyelitis optica spectrum disorder patients." (PMID 29497397, 2018).
neuropathy (1 paper, 2023). A disorder affecting the nervous system that manifests with pain, tingling, numbness, and/or muscle weakness. "In the case of CCL13, CCL14, and CCL16, to our knowledge, there are no data showing their influence on neuropathy in humans or even in animal models (excluding mice and rats, which do not express these chemokines)." (PMID 37570736, 2023).
oral cancer (1 paper, 2022). "This study demonstrated the pro-tumor roles of CCL13 in oral cancer and illustrated that stress granules appeared to a positive regulator of CCL13 expression in M2 TAMs via improving the DDX3Y/hnRNPF-mediated mRNA stability of CCL13." (PMID 36291863, 2022). "In the current study, we identified that G3BP1 can facilitate adaptive reactions of macrophages in response to adverse conditions in the tumor microenvironment, and these effects of G3BP1 simultaneously stimulated the expression of CCL13 from M2 TAMs, consequently improving oral cancer metastasis." (PMID 36291863, 2022).
primary biliary cholangitis (1 paper, 2023). Primary biliary cholangitis (PBC) is a chronic and slowly progressive cholestatic liver disease of autoimmune etiology characterized by injury of the intrahepatic bile ducts that may eventually lead to liver failure. "Even though CCL13-mediated inflammation is frequently linked to disease pathogenesis, it’s fascinating to note that in some conditions, like primary biliary cholangitis (PBC) and suicide, it might even act as a preventative measure." (PMID 37153575, 2023).
Pruritus (1 paper, 2025). Pruritus is an itch or a sensation that makes a person want to scratch. "These pathways include cytokines, such as IL-4, IL-13, IL-31, and TSLP, and chemokines, such as CCL1, CCL13, and CCL17, which have been implicated in barrier disruption, pruritus, and immune cell recruitment in AD." (PMID 41583462, 2025).
pulmonary fibrosis (1 paper, 2024). Chronic progressive interstitial lung disorder characterized by the replacement of the lung tissue by connective tissue, leading to progressive dyspnea, respiratory failure, or right heart failure. "Limited research on CCL13 in pulmonary fibrosis identifies blood CCL13 levels as a prognostic biomarker in IPF patients treated with placebo versus those treated with pirfenidone." (PMID 39768150, 2024). "Experimental studies on the role of CCL13 in pulmonary fibrosis are lacking due to its human-specific expression and absence in mice." (PMID 39768150, 2024).
RSV bronchiolitis (1 paper, 2025). "Plasma CXCL13 levels were also significantly higher in the RSV bronchiolitis group [258.76 (199.19, 354.66) pg/mL vs. 127.68 (82.43, 214.50) pg/mL; P < 0.001], as were plasma CCL13 levels [239.33 (125.11, 335.76) vs. 97.69 (54.38, 219.80) pg/mL; P < 0.001]." (PMID 41360931, 2025).
skin tumor (1 paper, 2021). "The skin tumor microenvironment contained potentially tumor-permissive myeloid cells producing regulatory (IDO1) and Th2-associated mediators (CCL13, CCL17, CCL22)." (PMID 33968070, 2021).
uveitis (1 paper, 2023). An inflammatory process affecting a part of or the entire uvea. "Studies have shown that people with HLA-B27-associated uveitis have 255-fold higher levels of CCL13 in their aqueous humor than healthy individuals." (PMID 37153575, 2023). "This suggests that CCL13 is involved in the pathogenesis of non-granulomatous uveitis and that the associated immune responses may be more effective in this type of uveitis, particularly in HLA-B27-associated uveitis." (PMID 37153575, 2023).
vitiligo (1 paper, 2025). Generalized well circumscribed patches of leukoderma that are generally distributed over symmetric body locations and is due to autoimmune destruction of melanocytes. "In contrast to the findings in vitiligo, Th2 signaling was prominent as well, with consistent upregulation of CCL13, CCL17, CCL22, and CX3CL1." (PMID 40969764, 2025).
tumor (48 papers, 2010 to 2025). "CCL13 plays a crucial role in the development of M2 tumor-associated macrophages (TAMs), a subset of macrophages often associated with immunosuppression, tumor angiogenesis, and tumor spread." (PMID 38275392, 2023). "Tumor-associated pre-cDC exhibit the same phenotypic and functional characteristics as bone-marrow and spleen pre-cDC and their migration depends on tumor expression of chemokine CCL13." (PMID 30979057, 2019). "Several investigations have reported a strong association between CCL7, CCL13, CXCL5, and CCR9 and tumorigenesis as well as tumor development." (PMID 41465903, 2025). "In cases of gastric cancer, the levels of CCL13 reflect the distinct response patterns of fibroblasts in specific tumor sites toward cancer cell invasion." (PMID 37153575, 2023). "The mRNA level of CCL13 was significantly higher in HCC tumor tissues than in HCC-adjacent tissues based on the TCGA dataset." (PMID 35281057, 2022). "CCL13 is widely expressed by different tissues under homeostasis conditions and is significantly increased in various tumor cell lines (A549, BEAS-2B)." (PMID 35281057, 2022). "We first analyzed the correlations between CCL13 expression, tumor purity and immune infiltration level of 6 immune cells." (PMID 34368124, 2021). "Whilst CCL13 triggers monocytes, T-cells and immature dendritic cells (DCs) to migrate towards the tumor." (PMID 32560387, 2020). "In the current study, we also found that especially four chemokines were upregulated in the recurrent tumor compared to the primary tumor; CCL13, CCL18, CCL19, and CXCL14." (PMID 33352957, 2020). "The strengthening effect on tumour behaviour induced by oestrogen treatment could be blocked when co‐treatment with CCL13 neutralizing antibody (anti‐CCL13)." (PMID 38680032, 2024). "In the xenograft mouse model, the supernatant from the co‐incubation of macrophages and oestrogen‐treated SKOV3 exosomes could promote tumour growth, as well as CCL13 treatment, which were suppressed by CCR2 knockdown." (PMID 38680032, 2024). "Elevated levels of CCL13 can be indicative of submucosal invasion by tumor cells." (PMID 37153575, 2023). "Interestingly, we found PTHLH derived from tumor cells can target macrophages and regulate the expression of CCL13, PLAU and ICAM1, resulting the phenotype of TAM_c1." (PMID 38044943, 2023). "Collectively, our findings demonstrated for the first time the roles of CCL13 in improving OSCC metastasis and illustrated the molecular mechanisms of CCL13 expression regulated by SG, indicating that the SG-CCL13 axis can be the potential targets for TAM-navigated tumor therapy." (PMID 36291863, 2022). "If the pro-metastasis effects of CCL13 can be demonstrated in the two cell lines with distinct metastatic potentials, the hypothesis about pro-tumor properties of CCL13 would be more persuasive." (PMID 36291863, 2022). "In addition, CCL13 has been found to lead to drug resistance in tumor cells by promoting cell apoptosis and drug resistance." (PMID 35281057, 2022). "CCL13 is a coding gene involved in immune regulation and inflammatory responses, and it has been reported that CCL13 has a role in promoting the proliferation of tumor-forming volume in nude mice." (PMID 32766727, 2020). "The cytokines of the first group include L1A, IL36A and CCL13, which, as immune stimulatory mediators, may contribute to an anti-tumor immune response and thus a favorable clinical outcome." (PMID 31588238, 2019). "ACKR1 on the surface of endothelial cells binds, clears and regulates various chemokines such as CXCL1, CXCL2, CCL13 and CCL18, which play key roles in angiogenesis and tumour progression." (PMID 39601163, 2024). "The interaction between ACKR2 and CCL13, CCL7 illustrates that SLC40A1+ TAMs and APOC1+ TAMs be recruited by ECs to modulate tumor immunity." (PMID 39232806, 2024). "The mRNA expression of CCL13 and KLRC1 in tumor tissues were significantly lower than that in the normal tissues." (PMID 34368124, 2021).
tumor (continued). "The results showed that KIAA1429, HAMP, AQP9, CCL13, and CCL21 were significantly negatively correlated with tumor purity, and KIAA1429 was highly correlated with B cells, CD8 T cells, CD4 T cells, macrophages, neutrophils, and dendritic cells." (PMID 34422053, 2021). "CCR5 binds many ligands which are overexpressed in the tumor microenvironment including CXCL13 (BCA-1), CCL3 (MIP1α), CCL3L1, CCL4 (MP-1β), CCL8 (MCP2), CCL11 (eotaxin), CCL13 (MCP-4), and CCL16 (HCC-4)." (PMID 33485378, 2021). "Here we demonstrate that the tumor microenvironment in GBM patient cohort can be profiled by M1-like and M2-like microglia/ macrophage markers CXCL10 (M1-like) and CCL13 (M2-like) and by a subset of metalloprotease genes." (PMID 31142630, 2019). "Intriguingly, tissues from individuals with metastatic salivary adenoid cystic carcinoma(SACC) showed higher expression of CCL13 in the absence of tumor recurrence or perineural invasion than in the presence of tumor recurrence." (PMID 37153575, 2023). "Monocyte chemoattractant protein-4 (MCP-4/CCL13) is a proinflammatory factor that is overexpressed in various malignant tumors and may play an important role in tumor progression and metastasis." (PMID 36531002, 2022). "The immunohistochemical data showed lower expression of G3BP1, CCL13 and CD206 in the group of mice implanted with SAS cells mixed with G3BP1-knockdown MDMs-M2 than in the control group, and smaller tumor sizes were observed in G3BP1-depleted group as revealed by H&E staining." (PMID 36291863, 2022). "Our findings that both SPP1 and CCL13, along with their respective interaction, are up‐regulated in F13A1+ Mφs indicate their involvement in shaping the immunosuppressive TME, facilitating tumour immune escape and promoting tumour proliferation and invasion in MPLC." (PMID 39601163, 2024). "The results showed that CCL13 expression level had negative correlation with tumor purity." (PMID 34368124, 2021). "Subsequent in vitro studies have shown that CCL13 released from senescence-inducing GBM cells overexpressing p16INK4A can recruit T cells to the tumor tissue, which may help construct a more immunogenic tumor microenvironment, thereby improving the prognosis of GBM patients." (PMID 41201287, 2025).